RB1 (RB transcriptional corepressor 1)
Diseases named in the same sentence as RB1 in open-access papers (continued):
Sharing a sentence is not in itself a finding about the gene and the disease.
cancer (continued). "Many of these associations group into well-known cancer pathways including the NFE2L2, RB1, MAPK, and Wnt pathways." (PMID 35382456, 2022). "Pathogenic variants in five “other” cancer predisposition genes (ALK, BUB1B, FANCG, RB1 and XPC) exclusively investigated for truncating variants, were identified in seven patients." (PMID 35039564, 2022). "Although dysfunction of RB1 is prevalent, the exact molecular mechanism for the malignant transformation of RB is still unclear and more genetic and epigenetic factors that are involved in this type of cancer remain to be discovered." (PMID 36096885, 2022). "While the mutation frequency in RB1 is typically greater than for RBL1 or RBL2, there are some cancer subtypes where this is reversed." (PMID 35368709, 2022). "In 25 analyses of 17 cancer types, we have identified 19 to 169 significant genes by copy deletion, including RB1, PTEN and CDKN2A as the most significantly deleted genes among all cancer types." (PMID 36726722, 2022). "Several cancer-related genes are located within genomic regions of increased susceptibility, including telomerase reverse transcriptase, TERT, thereby accelerating mutagenic potential in cancers with RB1 pathway alterations." (PMID 34983823, 2022). "Consistent with prior studies, we found these higher rates associated with homozygous deletions at the BRCA2 locus that often spans the proximal RB1 that is a common lineage-specific driver in these cancer types." (PMID 36418296, 2022). "The disruption of the interaction between Rb1 and these lineage-specific transcription factors results in impairment of differentiation, re-entry into the proliferative mode, and cancer development." (PMID 35267571, 2022). "The same approach was also utilized in recent studies to identify novel therapeutic opportunities against cancers with defective RB1 tumor suppressor." (PMID 35155432, 2022). "Since the majority of cancer cells have an intact RB1 gene and thus depend on CDK4/6 kinase activity for sustained proliferation, CDK4/6 emerged as a potential target for cancer therapy." (PMID 36067171, 2022). "More than 3 decades of research has firmly established a widespread and prominent role for RB1 in human cancer." (PMID 35368709, 2022). "The SPH3643 molecule displayed a stronger inhibition pattern and better specificity than abemaciclib and palbociclib, opening a new window for future CTs focused on the development of specific strategies in RB1-positive cancers." (PMID 35681689, 2022). "Rb1 function is deregulated in most types of human cancer through genetic alteration or, more often, through alteration of upstream pathway components that inactivate its function through post-translational modifications." (PMID 35267571, 2022). "Amacrine neurons and horizontal neurons are reported to initiate RB-like cancer in RB1/p107 mouse model and RB1/p130 mouse model, respectively." (PMID 36230849, 2022). "Most studies focus on RB1 because of its already established importance in cancer, but this only further reinforces the bias." (PMID 35368709, 2022). "The importance of the Rb1–E2F signaling axis in cancer is well recognized, however, the only clinically approved drugs targeting the pathway are CDK inhibitors." (PMID 35267571, 2022). "In non-cancer cells, RB1 is dephosphorylated by the cyclin-dependent kinase 4/6 (CDK4/6) pathway and can bind the transcription factor E2F, which prevents cell division." (PMID 34687436, 2022).
cancer (continued). "This review focuses on post-translational modifications, their effect on Rb1 interactors, and their role in intracellular signaling in the context of cancer development." (PMID 35267571, 2022). "This pRb-mediated effect on pluripotency is relevant to cancer as stem cell reprogramming factors like SOX2 are required for tumorigenesis initiated by RB1 loss." (PMID 35368709, 2022). "The pattern of RBL1 and RBL2 genetic alteration across cancer types is generally more similar to each other than to RB1, consistent with structural similarities between the paralogues." (PMID 35368709, 2022). "In cancer development Rb1 is considered a tumor suppressor and therefore its deletion is closely correlated with the development of several malignancies, in particular retinoblastoma." (PMID 35634242, 2022). "For most cancers the frequency of debilitating RB1 alterations is greater than the frequency of RBL1 or RBL2 alterations." (PMID 35368709, 2022). "Many cancer drivers that are also chromatin regulators, such as RB1, have broad impacts across the genome." (PMID 34983823, 2022). "We evaluated the clinicopathological correlates of the 7 SMGs, together with 6 additional cancer genes identified from at least 2 previous HCC genomics studies and mutated in ≥3 HCCs of the current cohort (APOB, ARID2, CDKN2A, KEAP1, RB1 and TSC2)." (PMID 35508466, 2022). "This review seeks to summarize the most recent research on Rb1 function and regulation and discuss potential avenues for the design of novel cancer therapies." (PMID 35267571, 2022). "More importantly, UNC5D, a potent tumor suppressor gene in most cancers is significantly up-regulated in Y79 and Weri Rb1 cells, which, in turn, questions its anti-cancer properties." (PMID 35359459, 2022). "In cancers with loss of the pRb function, RB1 inactivation mutation or dysregulation of pRb upstream modulators constitutively inactivates pRb, giving rise to uncontrolled cell division." (PMID 35650644, 2022). "Given the central role of Rb1 in regulating proliferation, its expression or function is altered in most types of cancer." (PMID 35267571, 2022). "RBL1 and RBL2 genetic alterations are not common in these neuroendocrine cancers, again indicating RB1 alteration has a unique role in this cancer context." (PMID 35368709, 2022). "In our analysis, 6 out of 18 genes (EIF4A3, RAN, PSMA3, CCNA2, POLR2D, CDC27) were scored as SL hits against RB1 in at least two human cancer cell lines screens." (PMID 33591981, 2021). "RB1 has to be intact for CKD4/6 inhibitors to impact cell cycle progression, and RB1-mutant cancers are resistant to CKD4/6 inhibitors." (PMID 34327137, 2021). "The RB1-targeted molecules involved in such phenotypic changes are good quarries for cancer therapy." (PMID 34359636, 2021).
cancer (continued). "Given that only two-thirds of RB1 disruption events in the present study were detectable by the canonical WES, we proposed a potential underestimate of RB1 disruption in previous WES studies of cancers." (PMID 34145257, 2021). "Here we summarize current understanding on possible therapeutic approaches targeting functional or genomic aberration of RB1 in cancers." (PMID 34359636, 2021). "While the RB1 gene is rarely altered in these cancers, the RB1 protein is disabled by cyclin E, CDK2 and/or CDK4/6 upregulation as well as by loss of the CDK inhibitors, p27 and p16INK4a, in essentially all MPNSTs." (PMID 34065204, 2021). "Meanwhile, it has been identified that two other gradients of ginsenoside, termed Rb1 and Rg1, can be carried by CNTs and induce an inhibitory effect on cancer development." (PMID 34111025, 2021). "Rbfox2 in the structure of SGs promotes cell proliferation by influencing and decreasing RB1 expression.Resveratrol inhibits Rbfox2 activity on RB1 and decreases cancer expansion by separating Rbfox2 from the structure of SGs." (PMID 35004322, 2021). "In particular, RB1 is a key inhibitor of cell cycle progression in HCC patients, and RB1 mutations are significantly associated with reduced cancer-specific and recurrence-free survival after resection in HCC patients." (PMID 34556802, 2021). "We identified another hypermethylated CpG loci other than RB1, suggested there is some hypermethylated regions in RB as like as other types of cancer." (PMID 33717678, 2021). "RABL6A promotes the proliferation and survival of several cancers, including MPNSTs, by negatively regulating RB1." (PMID 34065204, 2021). "As in many other cancer cells, human RB cell lines including Y79 and Weri‐Rb1 display high expression of UHRF1, at least partially by E2F‐mediated transcriptional upregulation." (PMID 32840881, 2021). "We further extended our analysis on other members of RB1 pathway, including CDKN2A (p16Ink4a), CCND1, CDK4, and CDK6, which are often mutated in different cancers." (PMID 33591981, 2021). "Remarkably, by isolating Rbfox2 from the structure of SGs, resveratrol inhibited its effect on Rb1 and effectively reduced the proliferation of cancer cells." (PMID 34604242, 2021). "The simultaneous loss of RB1 and SUCLA2 was detected in various cancer types with varied prevalence." (PMID 34359636, 2021). "To test the clinical relevance of Drosophila SL pairs of RB1 in human cancer patients, we used SPAGEfinder, which identifies pairwise gene expression states that are significantly associated with survival of cancer patients." (PMID 33591981, 2021).
cancer (continued). "The cdk4, cdk6, rb1, and e2f1 genes are expressed in a wide range of cancers according to analysis of the TCGA PANCAN database, which is composed of 12,839 samples." (PMID 32357912, 2020). "It has been reported that RB1 is a transcriptional regulator and tumor suppressor retinoblastoma protein in cancers." (PMID 32013999, 2020). "The AluSx element is located 3 kb upstream of the RB1 TSS and lies within the second intron of Linc00441, a lincRNA divergent to RB1, that has been shown to affect RB1 transcription in cancer cells." (PMID 33061937, 2020). "The aaRS profiles are compared to genes with established roles in cancer, including a tumor suppressor (RB1), a proto-oncogene (MYC), and a translation factor (eIF4E)." (PMID 33266490, 2020). "Numerous pre-clinical studies have demonstrated the beneficial effects of CDK4/6 inhibition for RB1-positive human cancers; however, drawbacks of this targeted therapy are coming to light." (PMID 32344731, 2020). "Inactivation of RB1 expression in cancer leads to the deregulated activity of the transcription of E2F1, E2F2, and E2F3." (PMID 32429447, 2020). "Cyclin-dependent kinase 4/6 controls the downstream transcriptional signals that regulate cancer cell proliferation through the phosphorylation of their canonical substrate RB1." (PMID 33282875, 2020). "Ectopic expression of the retinoblastoma protein (RB1) in RB1-null cancer cell lines results in senescence-like phenotype." (PMID 31910742, 2020). "Focusing on the TCGA pan-cancer study, which includes data from 33 cancer types, we first observed the CNV and mutational profiles of the tumor suppressor RB1, the proto-oncogene MYC, and the translation initiation factor EIF4E." (PMID 33266490, 2020). "The retinoblastoma tumor suppressor gene (RB1) plays a critical role in coordinating multiple pathways that impact cancer initiation, disease progression, and therapeutic responses." (PMID 32242058, 2020). "The efficacy of CDK4/6 inhibitors relies on the presence of wild-type RB1 in the cancer cells as inhibition of CDK4/6 blocks proliferation through the accumulation of hypo-phosphorylated RB1." (PMID 32344731, 2020). "RB1 was found to take part in dysregulation of human cancers, which was regulated by some miRNAs, including miR-26a and miR-335." (PMID 32013999, 2020). "In contrast to MYC and RB1, which are predominantly modified at the DNA level, aaRSs seem to be mostly dysregulated at the transcriptional level in cancer." (PMID 33266490, 2020). "We first detected the expression of Rb1 protein in cancer tissues and found that the expression of Rb1 was significantly lower than that in adjacent tissues (P<0.001)." (PMID 33083296, 2020). "Most significantly CDKN2A loss and RB1 loss are mutually exclusive in most cancers that lose these genes at a significant level (>5%), suggesting that the control of CDK4/6 activity and RB-status appear to define a single element of the pathway." (PMID 32242058, 2020).
cancer (continued). "The participation of pRb in these processes has been studied in vivo in mutant mice and/or cell cultures derived from cancer cells, characterized by alterations in their RB1 expression levels." (PMID 32664691, 2020). "RB1 loss links to increased mitochondrial OXPHOS, which links to enhanced anabolic metabolism and augmented cancer cell stemness and metastatic spread." (PMID 33489906, 2020). "Zhao L showed that miR-221-3p promotes cancer development by inhibiting RB1 to increase the resistance of PC cells to gemcitabine." (PMID 32943991, 2020). "Clustering analysis of the frequency of events targeting CDK4, CCND1, CDKN2A, and RB1 indicates analyzed human cancers fall into five distinct groups separated largely by RB1 status and the co-occurrence of CCND1, CDK4, and CDKN2A." (PMID 32242058, 2020). "Since the cloning of RB1, the biological function of the RB1 gene and its protein product (pRB) has become well-known in molecular genetics and cancer research." (PMID 31683923, 2019). "In our cohort, cancer-specific survival seems to be influenced by a complex pattern by RB1 and AKT molecules, depending on the LN involvement and molecular subtypes (mostly luminal A and B)." (PMID 31781306, 2019). "Especially, loss of functional tumor suppressor genes, including CDKN2A/B, PTEN, and RB1, is frequently observed across a broad range of cancer types, including GBM." (PMID 30898893, 2019). "In the present review, we explored short and long ncRNAs, which are deregulated in Rb, demonstrating that, in addition to RB1, there is a great number of other molecules involved in the development of the malignant phenotype of this type of cancer." (PMID 31798638, 2019). "We also compared the genes identified for LUAD and LUSC and found only five genes (ARID1A, CDKN2A, EGFR, MLL3, and RB1) are common for the two cancer types, demonstrating their different disease mechanism." (PMID 30828525, 2019). "The RB1 pathway, a key player in cell cycle progression, is frequently deregulated in many cancers, including BC, and it is considered to be a therapeutic target." (PMID 31591311, 2019). "We confirmed that Rbfox2 expression in cancer tissue was significantly elevated relative to that in normal tissue, whereas RB1 expression was markedly decreased in cancer tissue compared to normal tissue." (PMID 31028247, 2019). "Through in silico and in vitro analysis of different cancer types it has been possible to identify and validate miRNAs that directly regulate RB1 gene." (PMID 31798638, 2019). "Cyclin D2 is involved in the phosphorylation of RB1 and numerous studies have demonstrated that its expression levels are high in various cancers." (PMID 31798638, 2019). "The RB1 gene is considered to be a central regulator of the cell cycle mechanism and is inactivated in a wide range of cancers." (PMID 31798638, 2019).